ALDH7A1 (aldehyde dehydrogenase 7 family member A1)
Description:
Aldehyde dehydrogenase enzyme that mediates important protective effects. Protects cells from oxidative stress by metabolizing a number of lipid peroxidation-derived aldehydes. Involved in cellular defense against hyperosmotic stress by metabolizing betaine aldehyde to betaine, an important cellular osmolyte and methyl donor. [Isoform 1]: Involved in lysine catabolism in the brain by mediating the conversion of L-aminoadipate-semialdehyde ((S)-2-amino-6-oxohexanoate) to L-2-aminoadipate. [Isoform 2]: Acts as a key inhibitor of ferroptosis both by generating membrane NADH and decreasing the level of reactive aldehydes. Recruited to plasma membrane in response to ferroptotic stress and phosphorylation by AMPK, generating membrane NADH to support AIFM2/FSP1 activity, an essential ferroptosis suppressor protein. Also directly inhibits ferroptosis by decreasing lipid peroxidation via consumption of reactive aldehydes, such as 4-hydroxynonenal (4-HNE) and malonaldehyde. Also acts as a regulator of cellular energy homeostasis in response to cellular energy stress, such as starvation and hypoxia, by inhibiting COPI-mediated intracellular transport, thereby reducing cellular energy consumption.
Synonyms: ATQ1; EPD; PDE; EPEO4
Tractability: Small molecule: a structure with a bound ligand is known; it has a high-quality binding pocket; it belongs to a druggable protein family. PROTAC: ubiquitination databases record sites on it; its protein half-life has been measured.
Target class: Enzyme; Oxidoreductase
Gene: Protein-coding gene on chromosome 5 (126,531,200 to 126,595,362, reverse strand). Ensembl gene ENSG00000164904.
Subcellular location: Mitochondrion (Isoform 1); Cytoplasm, cytosol (Isoform 2); Cell membrane; Golgi apparatus membrane; Nucleus
Subcellular location (Human Protein Atlas): Mitochondria; Cytosol
Pathways (Reactome):
Metabolism: Choline catabolism; Lysine catabolism
Gene Ontology:
Molecular function: aldehyde dehydrogenase (NAD+) activity; betaine-aldehyde dehydrogenase (NAD+) activity; identical protein binding; L-aminoadipate-semialdehyde dehydrogenase [NAD(P)+] activity; protein binding; medium-chain fatty aldehyde dehydrogenase (NAD+) activity; oxidoreductase activity
Biological process: L-lysine catabolic process; aldehyde metabolic process; choline catabolic process; sensory perception of sound; amino acid catabolic process
Cellular component: cytosol; extracellular exosome; Golgi membrane; mitochondrion; nucleus; plasma membrane; mitochondrial matrix
Genetic constraint (gnomAD): Loss-of-function variants: 60 observed, 75.66 expected, observed/expected ratio (o/e) 0.79, 90% interval 0.64 to 0.98. The upper end of that interval is the gene's LOEUF score, 0.98, which puts it in group 4 of 6, group 1 being the genes least tolerant of losing a copy. Missense variants: 613 observed, 680.13 expected, observed/expected ratio (o/e) 0.9, 90% interval 0.84 to 0.96. Synonymous variants: 239 observed, 238.69 expected, observed/expected ratio (o/e) 1, 90% interval 0.9 to 1.12.
Gene-disease validity (ClinGen):
ClinGen rates the evidence that ALDH7A1 causes each of these diseases.
pyridoxine-dependent epilepsy (autosomal recessive): Definitive. A rare neurometabolic disease characterized by recurrent intractable seizures in the prenatal, neonatal and postnatal period that are resistant to anti-epileptic drugs (AEDs) but that are responsive to pharmacological dosages of pyridoxine (vitamin B6).
Homologues: Orthologues: macaque ALDH7A1 (99% identical), chimpanzee ALDH7A1 (97% identical), pig ALDH7A1 (96% identical), rabbit ALDH7A1 (96% identical), guinea pig ALDH7A1 (91% identical), mouse Aldh7a1 (88% identical), dog ALDH7A1 (87% identical), rat Aldh7a1 (83% identical), tropical clawed frog aldh7a1 (82% identical), zebrafish aldh7a1 (82% identical), Caenorhabditis elegans alh-9 (62% identical), Drosophila melanogaster Aldh7A1 (55% identical). Paralogues in human: ALDH1A2 (29% identical), ALDH1B1 (29% identical), ALDH1A1 (28% identical), ALDH1A3 (28% identical), ALDH1L2 (28% identical), ALDH2 (28% identical), ALDH1L1 (27% identical), ALDH9A1 (25% identical), ALDH5A1 (24% identical), ALDH8A1 (24% identical), ALDH6A1 (22% identical), ALDH16A1 (21% identical), and 5 more.
Diseases named in the same sentence as ALDH7A1 in open-access papers:
ALDH7A1 is named in the same sentence as 104 diseases in open-access papers, as found by Europe PMC text mining. Sharing a sentence is not in itself a finding about the gene and the disease. The quoted sentences say what the papers report.
pyridoxine-dependent epilepsy (31 papers, 2014 to 2026). "Pyridoxine-dependent epilepsy (PDE) due to recessive ALDH7A1 mutations is characterized by intractable epilepsy that is often unresponsive to antiseizure medications." (PMID 41221123, 2025). "Pyridoxine-dependent epilepsy related to ALDH7A1 deficiency (PDE-ALDH7A1; OMIM #266100) is a rare developmental epileptic encephalopathy characterized by refractory seizures that respond to a high dose of pyridoxine (vitamin B6)." (PMID 40843901, 2025). "Pyridoxine-dependent epilepsy (PDE) is identified as a rare neurometabolic disease marked by biallelic pathogenic mutations of the ALDH7A1 gene." (PMID 40800672, 2025). "Pyridoxine-dependent epilepsy (PDE) with ALDH7A1 gene variants (PDE-ALDH7A1) is a rare autosomal recessive etiology-specific developmental and epileptic encephalopathy (DEE)." (PMID 38419708, 2024). "By contrast, two other inborn errors of lysine degradation, glutaric aciduria type 1 (GA1) caused by mutations in GCDH (MIM 231 670) and pyridoxine-dependent epilepsy caused by mutations in ALDH7A1 (PDE-ALDH7A1; MIM 266 100), are serious diseases." (PMID 36128717, 2022). "Pyridoxine dependent-developmental and epileptic encephalopathy (PD-DEE) or pyridoxine-dependent epilepsy (PDE) is a rare autosomal recessive disorder caused by biallelic pathogenic variants in ALDH7A1." (PMID 36082373, 2022). "Pyridoxine-dependent epilepsy (mutations in ALDH7A1 and PROSC genes) is one of the most common inborn errors of metabolism that results in neonatal seizures." (PMID 33670692, 2021). "Pyridoxine-dependent epilepsy (PDE) is an autosomal recessive neurometabolic disorder due to a deficiency of α-aminoadipic semialdehyde dehydrogenase (mutation in ALDH7A1 gene), more commonly known as antiquitin (ATQ)." (PMID 35053812, 2021). "In the case of P8, ALDH7A1 variants associated with pyridoxine-dependent epilepsy were thought to be related to patient's seizures, and the administration of pyridoxine improved seizures in this patient." (PMID 32695065, 2020). "Pyridoxine dependent epilepsy (PDE) (OMIM#266100) caused by likely pathogenic variants in ALDH7A1 (PDE-ALDH7A1) (GenBank accession nos: GI319655560 GI320202963 and GI319655559) is an autosomal recessively inherited neurometabolic disease." (PMID 29053735, 2017). "Pyridoxine dependent epilepsy (PDE) is caused by likely pathogenic variants in ALDH7A1 (PDE-ALDH7A1) and inherited autosomal recessively." (PMID 29053735, 2017). "We identified other inherited metabolic disorders including pyridoxine-dependent epilepsy (PDE) due to biallelic variants in ALDH7A1, PYCR2 disease, EARS2 disease, PARS2 disease, CLN7 disease, and glucose transporter 1 deficiency syndrome with or without liver dysfunction in our study cohort." (PMID 34440401, 2021). "In the case of ALDH7A1 (P8), which is associated with the recessive disease pyridoxine-dependent epilepsy, two variants were identified near the intronic junction; these were not canonical splice variants but were reported as variants of uncertain significance owing to the lack of evidence." (PMID 32695065, 2020). "Pyridoxine-dependent epilepsy (PDE, OMIM: 266100) or ALDH7A1 deficiency (traditionally) and pyridox(am)ine-5′-phosphate oxidase (PNPO) deficiency (OMIM: 610090) are the most prevalent type." (PMID 35495162, 2022). "The most common B6RD is pyridoxine-dependent epilepsy-ALDH7A1, caused by biallelic pathogenic variants in ALDH7A1, which encodes for the alpha-aminoadipic semialdehyde dehydrogenase, antiquitin." (PMID 36324377, 2022). "Pyridoxine-dependent epilepsy (PDE, OMIM: 266100) is a clinical disorder that typically presents in infancy or early childhood, caused by a deficiency of aldehyde dehydrogenase 7 family member A1 (ALDH7A1) which was first identified in 2006." (PMID 33868381, 2021).
pyridoxine-dependent epilepsy (continued). "The second deleted gene is ALdehyde DeHydrogenase 7 family, member A1 (ALDH7A1, OMIM *107323) which encodes an enzyme involved in lysine metabolism; recessive mutations cause pyridoxine-dependent epilepsy (OMIM #266100)." (PMID 25701871, 2015). "Pyridoxine-dependent epilepsy (EPD), for instance, is due to mutations in the Aldehyde Dehydrogenase 7 Family, Member A1 (ALDH7A1) gene whose gene product metabolizes methyl donors and various aldehydes thereby protecting against oxidative stress." (PMID 25477785, 2014). "Pyridoxine-dependent epilepsy (PDE, OMIM code: #266100), also identified as pyridoxine-dependent developmental and epileptic encephalopathy, is a rare neurometabolic disease inherited from biallelic deleterious mutations in ALDH7A1 gene, situated at the 5q32.3 locus." (PMID 40800672, 2025). "It is also worth noting that some individuals with pyridoxine-dependent epilepsy do not have identified mutations in the ALDH7A1 gene." (PMID 35053812, 2021).
epilepsy (25 papers, 2015 to 2025). A brain disorder characterized by episodes of abnormally increased neuronal discharge resulting in transient episodes of sensory or motor neurological dysfunction, or psychic dysfunction. "Nine mutations found in ALDH7A1 show verified association with epilepsy-related conditions, while 11 mutations found in ALDH18A1 are confirmed with hereditary spastic paraplegia." (PMID 37373306, 2023). "While this form of epilepsy was known as early as the 1950's, its genetic origins were only identified in 2006 when biallelic variants in ALDH7A1, the gene encoding antiquitin, were found to be responsible for this neonatal epilepsy syndrome." (PMID 35250833, 2022). "AR forms of epilepsy can be severe with early-onset, such as epilepsy caused by variants in ALDH7A1, or have onset in adolescence or later as with variants in CSTB." (PMID 35911904, 2022). "It is important to differentiate between PNPO deficiency and other B6‐dependent epilepsies, including alpha‐aminoadipic semialdehyde dehydrogenase (ALDH7A1) deficiency and pyridoxal phosphate‐binding protein (PLPBP) deficiency." (PMID 32888189, 2021). "For epilepsy, limited studies have also implied a role of MEs via ME-mediated genomic rearrangements in CDKL5 and ALDH7A1 and de novo somatic L1 insertions biased toward epilepsy-associated genes." (PMID 34868252, 2021). "Another example in the study of epilepsy is the zebrafish aldh7a1 null mutant, which recapitulates the characteristics of pyridoxine-dependent epilepsy, caused by variants of the gene ALDH7A1." (PMID 34768904, 2021). "Mutations in ALDH5A1 cause 4-hydroxybutyric aciduria, and mutations in ALDH7A1 cause pyridoxine-responsive epilepsies." (PMID 34680056, 2021). "Vitamin B6-responsive epilepsies are a group of genetic disorders including ALDH7A1 deficiency, PNPO deficiency, and others, usually causing neonatal onset seizures resistant to treatment with common antiepileptic drugs." (PMID 31741821, 2019). "For example, ALDH7A1 deficiency results in pyridoxine-responsive epilepsies, and our analysis identified 13 common missense variants in ALDH7A1, which may also impact patients’ risk of developing a neurological disorder, warranting further investigation." (PMID 34680056, 2021). "Hence, diagnosis of different B6‐dependent epilepsies is best established by the identification of biallelic pathogenic variants in the ALDH7A1, PNPO and PLPBP genes." (PMID 32888189, 2021). "As reported in our previous article on the clinical aspects of this cohort, the birth prevalence of diagnosed ALDH7A1-related epilepsy appears to be increasing in Norway." (PMID 38419708, 2024). "In humans, the accumulation of AASA as consequence of mutations in ALDH7A1/Antiquitin, which is the ortholog of Arabidopsis ALDH7B4, leads to developmental retardation and epilepsy." (PMID 38619227, 2024). "Mutations in the ALDH7A1 gene (5q23.2; MIM 107323) encoding α-amino-adipic semialdehyde (α-AASA) dehydrogenase (antiquitin) lead to the disorder of lysine metabolism, which in turn causes epilepsy that poorly responds to therapy with anticonvulsants." (PMID 32916978, 2020). "One of the best-characterized cases diseases associated with lysine catabolism is pyridoxine-dependent epilepsy (PDE), caused by the loss-of-function mutations of the enzyme α-aminoadipate semialdehyde dehydrogenase (AASADH) (also known as antiquitin, and aldehyde dehydrogenase 7A1, ALDH7A1)." (PMID 41194801, 2025).
prostate carcinoma (18 papers, 2013 to 2024). A carcinoma that arises from epithelial cells of the prostate gland. "For example, ALDH7A1 has been implicated in prostate cancer metastatic activity after left ventricular injection (LVI) of a prostate cancer cell line, while ALDH3A1 has been shown to be associated with metastasis using a mouse tail vein injection model." (PMID 26445849, 2016). "It has been shown that when ALDH7A1 is knocked down, the stem cell progenitor subpopulation in a particular prostate cancer cell line decreased." (PMID 32256979, 2020). "For example, ALDH7A1 has been reported to regulate the cancer stem cell self-renewal in colorectal, prostate cancer, and glioblastoma as a downstream effector of Wnt pathway." (PMID 30220009, 2019). "ALDH7A1 is functionally involved with stemness and metastatic activity of prostate cancer and recurrence of non-small cell lung cancer." (PMID 28671577, 2017). "The isoform ALDH7A1 which we examined has been described as a marker of the CSC-like signature of prostate cancer cells, and as functionally involved in prostate cancer bone metastasis." (PMID 27764770, 2016). "Other ALDH isoforms have been mechanistically associated with metastatic behavior in vitro, including ALDH1A3 in breast cancer, melanoma, pancreatic cancer and brain cancer; ALDH3A1 in prostate cancer and liver cancer; and ALDH7A1 in prostate cancer." (PMID 26445849, 2016). "In breast cancer CIC, the ALDH1A3 isotype predominates and is predictive of metastasis, while in prostate cancer the ALDH7A1 isotype predominates." (PMID 24086346, 2013). "ALDH7A1 is generally known as a stemness marker in prostate cancer and is involved in the growth of pancreatic ductal adenocarcinoma and might thus be implicated in the maintenance of the undifferentiated phenotype of long-term repopulating HPV+ HNSCC cells." (PMID 39030166, 2024). "In addition, the expression of ALDH3A2 in adenocarcinoma, ALDH7A1 in prostate cancer and glioma, and ALDH9A1 in breast cancer and thyroid cancer is also high." (PMID 36651035, 2023). "IHC analysis further confirmed the dominant expression of ALDH7A1 in prostate cancer." (PMID 36651035, 2023). "ALDH7A1 has also been shown to be involved in the process of prostate cancer bone metastasis." (PMID 32256979, 2020). "A targeted network analysis of gene expression profiles in colorectal cancer cells revealed that ONC201 downregulates stem cell pathways such as Wnt signaling and modulates genes (ID1, ID2, ID3 and ALDH7A1) known to regulate self-renewal in colorectal, prostate cancer and glioblastoma." (PMID 28767654, 2017). "Based on various studies, it appears that the ALDH family has 19 isoforms that are expressed to a greater extent in the cancer of specific areas of the body; for example ALDH1A3 isoform in breast cancer, ALDH7A1 isoform in prostate cancer, and ALDH1A1 in pancreatic cancer." (PMID 28008389, 2016). "By analyzing six primary prostate cancer specimens and eight prostate cancer cell lines, it was indicated that ALDH isoforms with higher expression levels were ALDH3A2, ALDH4A1, ALDH7A1, ALDH9A1, and ALDH18A1." (PMID 37686694, 2023). "ONC201 significantly downregulated CSC-related genes ABCB5, ALDH1A1, ALDH7A1, WNT16, CD133 and NANOG in DU145 prostate cancer cells." (PMID 28767654, 2017). "Nevertheless, another study supports that ALDH7A1 and not ALDH1A1 was the primary enzyme isoform determining the high ALDH activity found in prostate cancer cells." (PMID 37686694, 2023).
breast carcinoma (6 papers, 2013 to 2026). "ALDH7A1, an isoform of aldehyde dehydrogenase, and a known breast cancer stem cell marker, assists in the breakdown of retinal to retinoic acid, aiding in the differentiation of breast stem cells." (PMID 32256979, 2020). "Utilizing the public CRISPR knockout screening datasets sourced from DepMap, we further supported our hypothesis that the essential roles of ADH5, ALDH1B1, and ALDH7A1 in breast cancer cell growth and development." (PMID 42196229, 2026).
Epileptic encephalopathy (5 papers, 2013 to 2026). A condition in which epileptiform abnormalities are believed to contribute to the progressive disturbance in cerebral function. "Pyridoxine-dependent epilepsy due to ALDH7A1 deficiency (PDE-ALDH7A1) is a rare but treatable epileptic encephalopathy caused by disruption of lysine catabolism and secondary depletion of pyridoxal-5'-phosphate (PLP)." (PMID 42072608, 2026). "ALDH7A1 deficiency is an epileptic encephalopathy whose seizures respond to treatment with supraphysiological doses of pyridoxine." (PMID 39038845, 2025). "There are various epileptic encephalopathies related to vitamin B6 metabolism, and pyridoxine-dependent epilepsy (PDE) is the prototype, resulting from a loss of the biologically active pyridoxal-5′-phosphate (PLP) due to a dysfunction of the protein antiquitin (ALDH7A1)." (PMID 23762547, 2013).
hyperprolinemia type 2 (4 papers, 2015 to 2025). Hyperprolinemia type 2 is an autosomal recessive proline metabolism disorder due to pyroline-5-carboxylate dehydrogenase deficiency. "Additionally, vitamin B6 is effective in conditions where metabolites accumulate and inactivate PLP, such as Aldehyde Dehydrogenase 7 Family Member A1 (ALDH7A1) deficiency and hyperprolinemia type II." (PMID 40871704, 2025). "Seizure onset mainly occurred in the neonatal period (67.8% of cases), while only ten patients presented with seizures after the age of 12 months (four with ALDH7A1 deficiency, three with PNPO deficiency, one with PLPBL, and two with hyperprolinemia type II)." (PMID 36980111, 2023). "PLP depletion is the main pathophysiological mechanism for different inborn errors of metabolism, including ALDH7A1 deficiency, PNPO deficiency, PLP binding protein deficiency, hyperprolinemia type II, hypophosphatasia, and glycosylphosphatidylinositol (GPI) anchor synthesis defects." (PMID 36980111, 2023).
lung carcinoma (4 papers, 2019 to 2025). "Moreover, ALDH7A1 was reported to promote tumor progression in both lung carcinoma and pancreatic ductal adenocarcinoma." (PMID 41502512, 2025). "Single nucleotide polymorphisms (SNP) in genes, such as ALDH7A1, POLA2, LIG1, and ERCC6L, are important for the development of various cancers, such as esophageal squamous cell carcinoma, lung cancer, and oral cancer, but these polymorphic genes may be linked with pathogenesis of BRCA." (PMID 31311202, 2019).
Obesity (4 papers, 2016 to 2023). Accumulation of substantial excess body fat. "Specifically, miR-193b regulates ALDH3A2 and let-7b interacts with ALDH7A1 in obesity, however, in liver cancer, miR-193b regulates ALDH7A1 and let-7b targets HADHA, they regulate different genes (miR-193b /ALDH7A1, let-7b/HADHA) that participate in the same functional process." (PMID 33121472, 2020).